RNA5S6 (RNA, 5S ribosomal 6)
Synonyms: RN5S6
Gene: Ribosomal RNA gene on chromosome 1 (228,621,447 to 228,621,565, reverse strand). Ensembl gene ENSG00000200624.
Gene Ontology:
Molecular function: structural constituent of ribosome
Cellular component: ribosome
Homologues: Paralogues in human: RNA5S1 (100% identical), RNA5S10 (100% identical), RNA5S11 (100% identical), RNA5S12 (100% identical), RNA5S13 (100% identical), RNA5S14 (100% identical), RNA5S15 (100% identical), RNA5S16 (100% identical), RNA5S17 (100% identical), RNA5S2 (100% identical), RNA5S3 (100% identical), RNA5S4 (100% identical), and 26 more.